MAP3K8 (mitogen-activated protein kinase kinase kinase 8)
Diseases named in the same sentence as MAP3K8 in open-access papers (continued):
Sharing a sentence is not in itself a finding about the gene and the disease.
tumor (continued). "One recent study determined that MAP3K8 knockout mice exhibited a significantly lower incidence of liver tumors compared with wild-type mice in diethylnitrosamine-induced tumor formation model." (PMID 27835990, 2016). "There is no existing tool for evaluating endogenous MAP3K8 kinase activity in tumours, the phosphorylated form of MAP3K8 being undetectable in protein extracts from tumours." (PMID 26456302, 2015). "For each type of experiments (IHC and western blots), the low- and high-MAP3K8 subgroups of HGSC tumours have been defined below and above the median value, respectively." (PMID 26456302, 2015). "Among the different MAP3K that control ERK activity, our team recently identified the kinase Tpl2 (Tumor progression locus, MAP3K8) as a potential new player in adipose tissue dysfunction and inflammation." (PMID 23316186, 2012). "This expression profile supports a possible tumor-suppressive function of MAP3K8 in this context." (PMID 40831931, 2025). "In addition to TNF and NF-κB, we also investigated the role of MAP3K8, also known as Cot or Tumor Progression Locus 2 (TLP2)." (PMID 40431657, 2025). "Although identified as a target, the frequency of this mutation is still under investigation with one retrospective analysis of spitzoid tumor samples finding that 33% of SM harbor a MAP3K8 fusion and two other cohorts finding only 8% of total Spitz lesions harbor a MAP3K8 fusion." (PMID 35747831, 2022). "MAP3K8 might play an essential role in tumor immunoregulation, which leads to pro-tumorigenic inflammation." (PMID 35004849, 2021). "MAP3K8 was found upregulated in multiple tumor types and closely related to tumorigenesis." (PMID 31552087, 2019). "In this way, MAP3K8 expression promotes tumor growth and progression as well as immune suppression." (PMID 30463908, 2018). "Moreover, MAP3K8 is up-regulated in multiple tumor types and is closely related to tumorigenesis and/or cancer progression." (PMID 30139984, 2018). "In lung and intestinal cancer, MAP3K8 is a tumor suppressor gene." (PMID 27835990, 2016). "However, MAP3K8 is predominantly considered a tumor-promoting oncogene in several tumor types, such as breast cancer, colon cancer, renal cell carcinoma, endometrial cancer, gastric cancer, nasopharyngeal carcinoma, thymoma and lymphoma." (PMID 27835990, 2016). "Interestingly, MAP3K8 protein levels exhibited a prognostic value, as overall survival was markedly shortened in patients whose tumours exhibited high MAP3K8 protein levels." (PMID 26456302, 2015). "Furthermore, we confirmed a greater MEK activation in the different tumours developed in a high-MAP3K8 PDX model (PDX1) compared with tumours from a low-MAP3K8 PDX model (PDX2), with a positive correlation between MAP3K8 protein level and MEK activation." (PMID 26456302, 2015). "The same tendency was observed, when considering either fully or partially resected tumours, although the number of tumours for which we had access to all required information (debulking status, MAP3K8 protein level and response to treatment) was quite low in the Curie cohort." (PMID 26456302, 2015). "A major issue is whether MAP3K8 has deleterious or beneficial effects on tumour growth and cancer patient outcome." (PMID 26456302, 2015). "MAP3K8 prognostic value in HGSC could not be explained by surgery efficiency or tumour stage, as there was an equal distribution of advanced stage or partially resected tumours in the low- and high-MAP3K8 subgroups of patients." (PMID 26456302, 2015). "Besides genes with metabolic functions, these include cell type-selective genes associated with immune regulation and tumor progression, e.g., LRP5, CD300A, MAP3K8 and ANGPTL4." (PMID 25968567, 2015). "Indeed, tumour growth inhibition was significantly higher in high-MAP3K8 PDX (60% in average) than in low-MAP3K8 PDX (16% in average)." (PMID 26456302, 2015).
tumor (continued). "In addition to that ccRCC patients with different clinical features had higher levels of MAP3K8 expression than the normal, we found that patients with ccB (P = 8.77E-4) and tumor grade 4 (P = 2.42E-2) subtypes expressed more MAP3K8 than that with ccA and tumor grade 3, respectively." (PMID 34567061, 2021). "Few significant interactions were observed between OS and clinicopathological features, indicating that tumor grade (P < 1.0E-4), patient race (P = 1.9E-2), and patient gender (P = 1.3E-2) may influence the prognosis of ccRCC patients with high-level MAP3K8 expression." (PMID 34567061, 2021). "However, whether MAP3K8 has deleterious or beneficial effects on tumor progression and clinical outcome of cancer patient is still highly controversial because of its multifaced roles and cross-talks with other molecular linchpins." (PMID 34567061, 2021). "Furthermore, we used regression coefficients for HERPUD1, MAP3K8, GAPDH, and DNAJB4 to construct risk score models as follows: risk score = −0.197∗MAP3K8 −0.261∗HERPUD1+ 0.185∗GAPDH+ 0.191∗DNAJB4 and calculated the risk score for each LUAD tumor sample." (PMID 34295900, 2021). "However, the role of miR-144-3p in RCC pathogenesis may not be clear as another study conversely suggested miR-144-3p both being decreased in RCC tissue and acting as a tumor suppressor by targeting mitogen-activated protein kinase 8 (MAP3K8)." (PMID 33042985, 2020). "ABLIM1, FHL5, and MAP3K8, on the other hand, were downregulated in ULMS, indicating their potential tumor-suppressive roles." (PMID 40831931, 2025). "Our analyses unveiled four hub genes—ABLIM1, FHL5, MAP3K8, and TOP2A—that consistently emerged as differentially expressed across all tumor samples when compared to normal tissue." (PMID 40831931, 2025). "Four hub genes—ABLIM1, FHL5, MAP3K8, and TOP2A—were consistently dysregulated in both tumor types relative to normal tissue, suggesting their common role in tumor development." (PMID 40831931, 2025). "Through analysis of the HPA database, we recognized remarkably higher expression levels of specific proteins, including AQP1, ITGA5, MAP3K8, PIK3R3, STC1, and TGM2, in HNSCC tumor tissues." (PMID 38688945, 2024). "In myeloma tumor cells, MAP3K8 acts as a mitogen in mitosis, induces MAP3K, and inhibits tumor cell apoptosis." (PMID 37239427, 2023). "In this investigation, it was observed that MAP3K1, MAP3K3, MAP3K5, MAP3K10, and MAP3K15 were upregulated in HCC tumor tissues, whereas MAP3K7, MAP3K8, MAP3K9, and MAP3K11 were downregulated in tumor tissues in GSE14520." (PMID 35311629, 2022). "MAP3K8, also known as TPL-2 or COT, has been demonstrated to have an effect on obesity 79, tumor phenotype 80, 81, atherogenesis 82 and mammalian inflammation." (PMID 33408787, 2021). "Considering its multiple tumor-promoting effects in various cancers, we focused on TGF-β signaling-related genes, namely TGFBR1, MAP3K8, and FURIN (red arrow)." (PMID 34537073, 2021). "For instance, MAP3K8 and AURKA identified by our phosphoproteomic interpretations are predictive biomarkers for treatment efficacy and mediators of anti-tumor activities in solid cancers." (PMID 32885042, 2020). "Using the TCGA database, we analysed MAP3K8, CCL20, VEGFC, and ANGPTL4 gene expression levels in both normal tissue and tumour tissue samples." (PMID 32019546, 2020). "For example, miR-375 inhibits CRC cell proliferation mainly through targeting both JAK2/STAT3 and MAP3K8/ERK signaling pathways, miR-30a regulates cell proliferation and tumor growth of CRC by targeting CD73, miR-374b regulates CRC cell apoptosis." (PMID 31998373, 2019). "Tumor progression locus 2, Tpl2 (also known as MAP3K8), is a serine-threonine protein kinase originally described as an oncogene, because its C-terminal truncation promoted tumor growth." (PMID 25781948, 2015).
tumor (continued). "Moreover, gene expression analysis showed that the expressions of KRT8 and S100A16 were significantly increased in tumor tissues, while the expressions of COL4A3, SMAD9, MAP3K8 and CCDC146 were decreased." (PMID 41239716, 2025). "MAP3K8 is a serine/threonine kinase that is widely expressed in immune cells, non-immune cells, and many tumor types." (PMID 35004849, 2021). "BRAFV600E positive cancer cell lines that express higher levels of MAP3K8 tended to be less sensitive to BRAF inhibitor drugs; MAP3K8 expression increased in the tumours of patients treated with BRAF inhibitors, and was even further elevated in drug resistance relapse tumour samples." (PMID 28282860, 2017). "Confirming the potential interest of MEK inhibitors for the treatment of HGSC patients with high MAP3K8 protein levels, we observed that both MEK inhibitors markedly reduced tumour growth in high-MAP3K8 PDX models, compared with low- or intermediate-MAP3K8 PDX models." (PMID 26456302, 2015). "It would thus be interesting, to uncouple MAP3K8 function in epithelial cancer cells and in immune cells to have a clear answer about MAP3K8 function in tumour development, considering both cell-autonomous and non-cell-autonomous functions." (PMID 26456302, 2015). "Even though the highly expressed miR-144-3p can inhibit the EMT of tumor tissues and cells by targeting EZH2, PBX3, and MAP3K8, we found that EMT could be negatively regulated by miR-144-3p through the ROS/NRF2/Notch1/Snail pathway in high-glucose-stimulated LECs." (PMID 33274006, 2020). "MAP3K8 proto-oncogene activation could trigger the MAPK cascade and regulate the MEK/ERK/JNK, TLR, and IKK/NFKB pathway responses, which not only play decisive roles at different stages of tumor development but also affect immune surveillance and responses to anti-cancer therapy." (PMID 36768307, 2023). "Notably, we identified EOCRC tumor-specific splicing of ZBTB7B (Th-POK), a zinc finger transcription factor which controls T-cell differentiation into CD4+ or CD8+ T-cells, and MAP3K8 (TPL2), a driver of oncogenic inflammation, though the biological function of these splice variants remains unknown." (PMID 38680862, 2024). "Moreover, studies have found that anti-tumor cytotoxicity of T lymphocytes could be promoted in cancer patients through activation of TLR-mediated MAPK and NFKB signaling pathways, suggesting whether TLR pathway regulates functions of TILs via MAP3K8 cascades need to be further studied." (PMID 34567061, 2021).
cancer (54 papers, 2011 to 2025). A tumor composed of atypical neoplastic, often pleomorphic cells that invade other tissues. "Although MAP3K8 was originally recognized as an oncogene since its discovery in 1991, genetic sequence analyses identified rare MAP3K8 mutations which is much less than altered expression and abnormal activation in human cancers." (PMID 34567061, 2021). "However, in another study, miR-589-5p was found to inhibit the stemness of LIHC cancer stem cells (CSCs) through MAP3K8 and miR-589-5p down-regulation in LIHC is associated with a poor clinical prognosis." (PMID 33861762, 2021). "In contrast to TOP2A, the remaining three genes—ABLIM1, FHL5, and MAP3K8—exhibit more context-dependent roles in cancers." (PMID 40831931, 2025). "MAPK kinase kinase 8 (MAP3K8) (also known as tumour progression locus 2 (TPL2)) is a cancer Osaka thyroid (COT) oncogene." (PMID 39030600, 2024). "This list contains physiologically relevant genes for macrophage and cancer biology, such as MAP3K8." (PMID 37359548, 2023). "Mitogen-activated protein kinase 8 (MAP3K8) is a vital component of the MAPK pathway and is associated with the development and progression of various cancers." (PMID 36768307, 2023). "Patients with stage 3 and stage 4 STAD had a higher expression of MAP3K8 in cancer tissues as compared to the patients at stages 2, 1, and the patients in the control group." (PMID 36768307, 2023). "MAP3K8 also acts as a prognostic biomarker for various cancers including, renal clear cell carcinoma, glioma, and high-grade serous ovarian carcinomas." (PMID 36768307, 2023). "Our study novelty found that MAP3K8 can mediate ALKBH5 activation of the classical cancer-promoting pathways ERK and JNK." (PMID 35982895, 2022). "miR-589-5p limits MAP3K8 expression and causes suppression of CD90+ cancer stem cells in hepatocellular carcinoma." (PMID 35087589, 2022). "miR-144-3p and miR-509-3p participate in the inhibition of cancer cell proliferation by inactivating MAP3K8 in renal cell carcinoma." (PMID 35087589, 2022). "Most of the genes in the subnetworks were inflammatory cytokines and participated in TNF signaling pathways and pathways in cancer, such as Ccl2, Ccl20, Csf1, Cx3cl1, Cxcl1, Cxcl3, Il6, Birc3, Map3k8, Nos2, Nfkb2, Tnfrsf1b, and Vcam1." (PMID 33042984, 2020). "The dual role of Tpl2 and its cancer type dependence are also evident from its expression patterns in The Cancer Genome Atlas (TCGA) datasets where downregulation of MAP3K8 occurs in some cancers and upregulation occurs in others." (PMID 29485707, 2018). "MAP3k8 was increased in cancer compared to control by 1.51-fold, p = 0.11 (RT-PCR) vs. 1.57-fold, p = 0.001 (microarray)." (PMID 25705890, 2015). "Subsequently several reports have found elevated MAP3K8 activity in a number of human cancers including breast, endometrial, thymomas, lymphomas, lung, Hodgkin’s disease, and nasopharyngeal carcinoma." (PMID 23457529, 2013). "An analysis of MAP3K8 expression data from the TCGA and GSE51575 databases revealed that MAP3K8 was expressed more in cancer tissues as compared to the adjacent control tissues and the expression of MAP3K8 was inversely proportional to the disease-free progression of GC." (PMID 36768307, 2023). "Therefore, because of the multiple pathways regulated by MAP3K8 in cancer progression, MAP3K8 and the MAPK cascade have remained attractive targets for new cancer therapy targets." (PMID 36768307, 2023). "Moreover, this study reminds us of the potential roles of MAP3K8 in cancer-related immunity in ccRCC." (PMID 34567061, 2021). "According to previous studies and the results in this study, effects of MAP3K8 on cancer-related inflammation in ccRCC may be double-edged." (PMID 34567061, 2021). "Thus, our results suggested that low expression of miR-375 activates JAK2/STAT3 and MAP3K8/ERK pathways in cancer cells, which in turn promotes cell proliferation." (PMID 28186962, 2017).
cancer (continued). "As MAP3K8 acts as an oncogene in numerous cancer types and the MEK gene is also involved in a wide variety of cellular processes such as proliferation, the down-regulation in the expression of these miRNAs could facilitate the oncogenic effects of MAP3K8/MEK in the growth of CT PitNETs." (PMID 32545591, 2020). "MEK can be directly activated by CRAF expression, as well as in a RAF-independent manner via protein kinase cancer Osaka thyroid (COT, also known as TPL2, MAP3K8) to activate the MAPK pathway." (PMID 39534873, 2024). "Tumor progression locus 2 (TPL2, also known as cancer Osaka thyroid (Cot) and MAP3K8) is a serine/threonine kinase that was initially identified as an oncogene and a target for provirus integration." (PMID 32724474, 2020). "For instance, MAP3K8, MAP3K13, NCF2, NF-κB (family), NFATC2, NF-κB (complex), and NR2F2 were significantly disturbed by myricetin treatment, which are belonging to cancer related MAPK/NF-κB inflammatory signaling pathway." (PMID 30956980, 2019). "Moreover, as MAP3K8 is an integral part of the MAPK cascade, which plays a pivotal role in various cancers’ progression and drug resistance, it was selected for further studies." (PMID 36768307, 2023). "In addition to downstream targets of NFκB, we also recovered important upstream regulators for cancer development and progression, including STAT3, MAP3K8, and TNF." (PMID 27078000, 2016). "MAP3K8 is a mediator of the non-canonical TGF-β signaling pathway, proposed to be a proto-oncogene that activates the downstream MEK-ERK pathway in various cancers." (PMID 34537073, 2021).
infection (27 papers, 2013 to 2024). The state of being infected such as from the introduction of a foreign agent such as serum, vaccine, antigenic substance or organism. "Given that TPL-2 is downstream of TLR4 and IL-1R-signaling and that TPL-2-deficent mice are more susceptible to bacterial infection due to reduced TNFα and IL-1β secretions, we analyzed the changes in microbiota following infection of WT and Map3k8–/–mice." (PMID 28759611, 2017). "These fold change values were then compared to each other (x-axis) creating a ratio of ratios plot to identify genes that were significantly different in Map3k8–/–mice at D5-post infection (x-axis)." (PMID 28759611, 2017). "Using co-housing experiments, we found resistance to infection in TPL-2 deficient mice (Map3k8–/–) was independent of microbiota alterations in H. polygyrus infected WT and Map3k8–/–mice." (PMID 28759611, 2017). "Moreover, Map3k8 is essential for mounting an effective immune response during infection." (PMID 28694430, 2017). "Specifically in the module, we find genes induced in response to infection such as IL1B, TNF, IL6, IL12B, NFKBIA, JUN, and MAP3K8, which are related to Toll-like receptor signalling (Appendix B)." (PMID 33498280, 2021). "The genes, Ccl2, Ccl20, Csf1, Cx3cl1, Cxcl1, Cxcl3, Il6, Birc3, Map3k8, Nos2, Nfkb2, Tnfrsf1b, and Vcam1, played core roles in a PPI network, and interacted closely with other ones in the infection." (PMID 33042984, 2020). "Using murine models with deletion of TPL-2 in all cells (Map3k8–/–), we identified the absence of TPL-2 protein was important for mediating protection against infection by the worm." (PMID 28759611, 2017).
MAP3K8 also shares sentences with these, for which no sentence is quoted: inflammatory bowel disease (11 papers); colitis (8); prostate carcinoma (7); rheumatoid arthritis (6); bacterial infection (5); chronic myeloid leukemia (5); papilloma (5); viral infection (5); Autoimmunity (4); colon cancer (4); influenza (4); leukemia (4); cervical cancer (3); Fulminant hepatitis (3); gastric tumor (3); immune diseases (3); inflammation (3); metabolic disease (3); multiple sclerosis (3); nasopharyngeal carcinoma (3); pancreatitis (3); T-cell lymphomas (3); ulcerative colitis (3); adenoma (2); candidiasis (2); colon adenocarcinoma (2); Crohn disease (2); cystic fibrosis (2); diabetes (2); gastric adenocarcinoma (2).
A further 66 diseases each share a sentence with MAP3K8 in 2 papers or fewer.